RN7SL845P (RNA, 7SL, cytoplasmic 845, pseudogene)
Gene: Miscellaneous RNA gene on chromosome 7 (152,757,662 to 152,757,951, forward strand). Ensembl gene ENSG00000244328.
Homologues: Orthologues: chimpanzee Metazoa_SRP (96% identical), macaque Metazoa_SRP (92% identical). Paralogues in human: RN7SL2 (82% identical), RN7SL1 (82% identical), RN7SL3 (81% identical), RN7SL712P (80% identical), RN7SL804P (80% identical), RN7SL127P (79% identical), RN7SL769P (79% identical), RN7SL665P (79% identical), RN7SL126P (79% identical), RN7SL186P (78% identical), RN7SL586P (78% identical), RN7SL732P (78% identical), and 705 more.